IRS1 (insulin receptor substrate 1)
Diseases named in the same sentence as IRS1 in open-access papers (continued):
Sharing a sentence is not in itself a finding about the gene and the disease.
breast cancer (continued). "In this study, we seek to investigate the contributions of IGF2 and the insulin receptor substrate-1 (IRS1) to Herceptin resistance and elucidate the underlying mechanism of increased expression of both IGF2 and IRS1 and aberrant activation of IGF-1R signaling in Herceptin-resistant breast cancer." (PMID 33976188, 2021). "Collectively, we demonstrate that the IGF2/IGF-1R/IRS1 signaling is aberrantly activated in Herceptin-resistant breast cancer via disruption of the FOXO3a-miRNA negative feedback inhibition." (PMID 33976188, 2021). "Additionally, the overexpression of miR-152 inhibits breast cancer cell proliferation via targeting IGF1R and IRS1 and suppressing their downstream AKT and MAPK/ERK signaling pathways." (PMID 33291523, 2020). "Our group described PTP-BL role in adipocyte differentiation 10 and reported the first evidence of PTPN13 tumor-suppressive, anti-growth factor effect, via insulin receptor substrate 1 (IRS1) dephosphorylation, in human breast cancer cell lines incubated with anti-estrogens 11-13." (PMID 31938048, 2020). "Phenformin also blocked epithelial-mesenchymal transition, decreased the invasive phenotype, and suppressed receptor tyrosine kinase signaling, including insulin receptor substrate 1 and IGF1R, in ErbB2-overexpressing breast cancer cells and mouse mammary tumor-derived tissues." (PMID 28947975, 2017). "In tamoxifen-resistant breast cancer cells, EGFR and ErbB3 recruit and phosphorylate IRS1." (PMID 27765041, 2016). "Moreover, a dynamic interplay between IGF and ERα in breast cancer cells has been demonstrated, where IGF-1R increase ERα phosphorylation and activity via mTOR/S6K1 and ERα mediates IGF-1R, IRS-1 and IGF ligand expression." (PMID 27765027, 2016). "Moreover, we found that IGF-1Rki affects HR in ovarian and breast cancer cells by reducing the expression of RAD51 at the mRNA level, and this subsequently decreased RAD51 protein level and its interaction with IRS-1." (PMID 26510816, 2015). "Oestrogens may also regulate IGF-stimulated cell migration via increased IRS-1 and IRS-2 expressions as these are both involved in breast cancer cell migration." (PMID 23983688, 2013). "The main way that oestrogens potentiate the response of breast cancer cells to IGFs is probably by induction of the expression of components of the IGF signal transduction pathway including type I IGF receptor, IRS-1, and IRS-2." (PMID 23983688, 2013). "In breast cancer, activation of the IGF-1R could result in stimulation of proliferation and metastasis through activation of insulin receptor substrate-1 and insulin receptor substrate-2." (PMID 23663564, 2013). "Herein, we sought to determine whether IGF-IR requires IRS-1 and -2 to transduce its biological effects, and whether these IRS proteins mediate distinct aspects of IGF-IR action in breast cancer cells." (PMID 17043687, 2006). "Previous work from our lab and others suggests that IRS-1 and -2 may mediate different aspects of IGF-IR action in breast cancer cells in vitro." (PMID 17043687, 2006). "Finally, based on the results of five validation data sets and the support of existing literature, we hypothesized that IRS1 and PRC1 may play an important role in breast cancer resistance." (PMID 35387129, 2022). "However, in breast cancer, which has been studied the most extensively of all cancers for IRS expression, there is also evidence that the expression of IRS-1 could correlate negatively with tumor progression." (PMID 19534786, 2009). "IRS-2, like IRS-1, can promote tumor initiation and progression when this adaptor protein is overexpressed in the mammary gland, a finding that would appear to conflict with the inability of IRS-2 to regulate tumor proliferation in human breast carcinoma cell lines." (PMID 19534786, 2009).
breast cancer (continued). "However, it has been more difficult to examine the function of IRS-1 in breast cancer cells as stable transfection of an antisense IRS-1 expression vector is not tolerated by breast cancer cells (data not shown)." (PMID 17043687, 2006). "Downregulation of IRS-1 is not well tolerated by breast cancer cells." (PMID 17043687, 2006). "In breast cancer, STAT6 plays a key role in inhibiting growth and inducing apoptosis, as it is activated by IL-4 independent of IRS-1." (PMID 40733498, 2025). "Studies have found that IGF2/IGF-1R/IRS1 signal pathway is normally inhibited through negative feedback to maintain basic cell survival and proliferation in HER2-positive human breast cancer cells." (PMID 34837929, 2021). "Here, that CPT indicated significant inhibition on both phosphorylated sites, S473 and T308 of AKT in MCF‐7 breast cancer cells, is not related to interference of PTEN, PI3K(p85) and PI3K(p110), but due to dephosphorylation of IRS1." (PMID 28272775, 2017). "In breast cancer cell lines, we showed that PTPN13 has a negative effect, via insulin receptor substrate 1 (IRS1) dephosphorylation, on the activation of PI3K, one of the driver pathways in ovarian cancer." (PMID 29221157, 2017). "Consistent with this, overexpression or knockdown of IRS1 and IRS2 had little or no affect upon ErbB2 action in both mouse and human mammary epithelial and breast cancer cells." (PMID 27765041, 2016). "Of note, all GAB1-selective or IRS1-selective inhibitors showed much better IC50 against T47D and MDA-MB-231 breast cancer cell lines than the non-tumorigenic MCF-10A cell line." (PMID 25569504, 2015). "Several studies have since demonstrated that IGF-1 promotes cell motility and invasion in human breast carcinoma cell lines and mouse mammary tumor cells that signal preferentially through IRS-2, but not in cell lines that express only IRS-1." (PMID 19534786, 2009). "The association of IRS-2 with tumor progression was first indicated by the finding that inhibition of the IGF-1R in ER- breast carcinoma cells, which express IRS-2 and lack or have decreased IRS-1 expression, does not inhibit tumor proliferation." (PMID 19534786, 2009). "Taken with our previously published reports, these data support a role for IRS-1, but not IRS-2, in IGF-stimulated growth of breast cancer cells." (PMID 17043687, 2006). "Here, we report that the IGF-IR is unable to mediate biological effects in the absence of IRS-1 and -2 expression, and directly demonstrate that these adaptor molecules mediate distinct aspects of IGF-IR action in breast cancer cells." (PMID 17043687, 2006). "The loss of S6kinase-dependent negative feedback loop, involving expression of the insulin receptor substrate 1 (IRS-1), leading to the activation of PI3K/Akt and Ras/MAPKinase has been observed in breast cancer cell lines and human breast and colorectal carcinomas after everolimus treatment." (PMID 28454119, 2017). "As IRS-1 and IRS-2 are thought to mediate most of the effects of IR and IGF-1R in breast cancer cells, it may be possible to disrupt this molecule without affecting normal glucose homeostasis mediated by other adapter proteins in insulin target organs." (PMID 29152592, 2017). "This may imply that targeting GAB1 or IRS1, but not AKT1, might be a better targeted strategy for breast cancer treatment." (PMID 25569504, 2015).
Hyperglycemia (108 papers, 2009 to 2026). An increased concentration of glucose in the blood. "Another observed causal affect is via IRS1/2 which are involved in the development of hyperglycemia and cardiovascular disease." (PMID 37569355, 2023). "For example, in the liver, inhibition of gluconeogenesis by the insulin receptor substrate (IRS) 2 pathway is impaired, while lipogenesis by the IRS1 pathway is preserved, thus causing hyperglycemia and hyperlipidemia." (PMID 27247938, 2016). "Null of IRS1 in mice causes not only insulin-resistant and hyperglycaemia, but also significant growth retardation during intrauterine and smaller size than wild-type (WT) littermates postnatal age in 4 months." (PMID 25978640, 2015). "IRS1 is primarily associated with glucose metabolism and hyperglycemia." (PMID 35241081, 2022). "In the PT, IRS2-dependent stimulation of sodium reabsorption could cause hypertension and edema, while impaired IRS1-dependent signaling could induce unsuppressed gluconeogenesis, possibly contributing to hyperglycemia." (PMID 27247938, 2016). "IRS1 signaling deficiency in the proximal tubule may impair IRS1-mediated inhibition of gluconeogenesis, which could induce hyperglycemia by preserving glucose production." (PMID 27247938, 2016). "In the kidney, impairment of IRS1-dependent inhibition of gluconeogenesis in the proximal tubule contributes to hyperglycemia, whereas IRS2-dependent signaling remains intact." (PMID 40725728, 2025). "The IRS1, identified in this study asdownregulated in the context of stress-induced hyperglycemia, plays a key role incellular glucose transport and insulin signaling." (PMID 40179269, 2025). "JNK is activated by hyperglycemia and free fatty acids, promoting cardiomyocyte apoptosis and interfering with insulin receptor substrate-1 (IRS-1) signaling, thus suppressing PI3K/Akt activity." (PMID 40710791, 2025). "Cytokines, fatty acids, hyperglycemia, mitochondrial dysfunction, endoplasmic reticulum (ER) stress, and insulin induce inhibitory Ser/Thr phosphorylation of IR, notably IRS-1 and -2, via JNK, IKK, traditional and novel PKCs, mTORC1/S6K, and MAPK." (PMID 40141412, 2025). "Gene variations (p.G972R, and p.T608R) of insulin receptor substrate 1 (IRS-1), PI3K and (R274H, R208 K and R467W) and in AKT2 were reported to be associated with T2D, fasting hyperglycemia and postprandial hyperinsulinemia." (PMID 37754255, 2023). "The elevated IL-6 values found after BD confirm the hyperglycemia and the lower IRS-1 expression detected, being this myokine contributing to the general BD-IR process." (PMID 37676577, 2023). "Further, disruption in IRS1/2 phosphorylation by insulin-dependent kinase was found in hyperglycemia conditions." (PMID 35431967, 2022). "Consistently, in insulin-resistant Albino Wistar rats, a GSP diet (100 mg/kg) improves hyperglycemia and hyperinsulinemia, increasing tyrosine phosphorylation of IR-β and IRS-1 and decreased serine phosphorylation of IRS-1." (PMID 34439477, 2021). "In the context of hyperinsulinemia and hyperglycemia, adipocyte-derived exosomes induce a proinflammatory phenotype in macrophages, which in turn decrease the insulin receptor substrate 1 (IRS-1) and hormone-sensitive lipase (HSL) expression in adipose tissue." (PMID 34959338, 2021). "One consequence of this is ubiquitin-mediated destruction of IRS-1/2, resulting in deficits in glucose uptake and systemic hyperglycemia." (PMID 32193527, 2020). "According to this study, the hyperglycemia in T2D patients induces the platelet activation through miR-144 and miR-223 to foster the “downregulation of IRS-1 expression and upregulation in the P2Y12 expression” via IRS-1-PI3K-Akt signaling." (PMID 32937836, 2020). "In support of this, we show that these mice exhibited downregulated Irs-1 and Glut4 expression, hyperglycemia, insulinemia, and impaired glucose clearance." (PMID 32796650, 2020).
Hyperglycemia (continued). "The deletion of both IRS1 and insulin receptor substrate 2 (IRS2) (H-DKO mice: heart-specific IRS1 and IRS2 double gene knock-out) in the brain and liver causes hyperglycemia, but such deficiencies in the pancreas and heart cause organ failure." (PMID 29484207, 2018). "Hyperglycemia promotes AGEs production, which inhibit tyrosine phosphorylation of IRS-1 and IRS-2 and decrease activation of the PI3-K/Akt pathway by activation of phosphokinase C (PKC)." (PMID 27413253, 2016). "Down-regulation of IRS-1 mRNA expression in skeletal muscle inhibited the stimulatory effect of insulin on glucose utilization further contributing to hyperglycemia." (PMID 24312573, 2013). "Increasing the protein levels of IRS1 will ultimately lessen the consequences associated with hyperglycaemia, as research has shown that animal models lacking IRS1 developed hyperglycaemia or T2DM." (PMID 37936909, 2023). "Thiazolidinediones can prevent or reverse the toxic effect of hyperglycemia on tyrosine kinase, promote the phosphorylation of IRS‐1, increase the level of GLUT‐4 mRNA and protein in the skeletal muscle of insulin‐resistant mice, and promote the translocation of GLUT‐4 in the skeletal muscle." (PMID 33650786, 2021). "Therefore, the impaired insulin signaling in the gastrocnemius muscles represents a mechanism for the induction of post-ischemic hyperglycemia through TNF-α-mediated IRS1 inhibition, with R-7050 improving this impairment." (PMID 34073455, 2021). "Our present findings clearly showed that the novel triterpenoid compounds from C. fistula controlled hyperglycemia through activation of IRS-1/Akt-mediated insulin signaling mechanisms and through regulation of carbohydrate metabolic enzymes in the skeletal muscle and liver." (PMID 34833905, 2021). "Consequently, the role of phosphorylation of Irs1 and Akt in signaling pathways is very crucial in anti-hyperglycemia and insulin sensitivity." (PMID 31736878, 2019). "In addition, hyperglycemia decreased tyrosine phosphorylation of the insulin receptor substrate-1 (IRS-1) as well as phosphorylation of protein kinase Akt and the expression of insulin-sensitive glucose transporter GLUT4." (PMID 28042862, 2016). "It remains to be shown whether impaired IRS2 or IRS1 signaling in response to hyperglycemia and possibly to FFAs is mediated through induction of ER stress in β-cells." (PMID 19305497, 2009). "In addition, hyperglycemia may activate platelets through miR-144 and miR-223 to downregulate IRS1 and upregulate P2Y12 expression in the platelets via IRS1/PI3K/AKT pathways." (PMID 36589857, 2022). "Thus, in the PP zone, where Irs1 is less abundantly expressed and Irs2 expression is downregulated, insulin signalling is impaired despite the hyperinsulinemia, leading to the impaired suppression of gluconeogenesis and hyperglycaemia." (PMID 27708333, 2016). "On the basis of these findings, we hypothesized that under the HF condition where the expression of Irs2 is downregulated, deletion of Irs1 leads to impaired insulin signalling in both the PP and PV zones, resulting in hyperglycaemia and suppression of steatosis." (PMID 27708333, 2016). "Thus, knockout of Irs1 in the PP zone impaired the insulin action of suppressing gluconeogenesis, resulting in marked hyperglycaemia, and knockout of Irs1 in the PV zone impaired the insulin action of stimulating lipid synthesis and storage, preventing steatosis." (PMID 27708333, 2016). "Metabolic analyses reveal that deletion of the Pdk4 gene had better improvement in hyperglycemia and glucose tolerance than knockout of the Pdk2 gene whereas the Pdk2 gene deletion showed better insulin tolerance as compared to the Pdk4 gene inactivation on the Irs1/2 knockout genetic background." (PMID 23940800, 2013). "The insulin receptor substrate-1 (IRS-1)/PI3K/Akt signalling axis is disrupted, contributing to reduced glucose transport and leading to hyperglycaemia." (PMID 40216734, 2025).
Hyperglycemia (continued). "They activated the PI3K/Akt pathway, which regulated IRS‐1, Akt, and GSK‐3 phosphorylation and GLUT4 translocation to reduce hyperglycemia." (PMID 39479631, 2024). "This inflammatory milieu triggers IR via serine phosphorylation of insulin receptor substrate-1 (IRS-1), ultimately leading to hyperglycemia and chronic exposure to elevated blood glucose levels contributes to beta cell dysfunction." (PMID 39006367, 2024). "Benzyl isothiocyanate enhances Nrf2-dependent antioxidant defense, mediates skeletal muscle IRS-1/AKT/TBC1D1 signalling, and improves GLUT4 expression, thereby ameliorating high-fat diet-induced hyperglycemia." (PMID 37779908, 2023). "Mice with liver-specific double IRS1 and IRS2 knockout exhibit severe hyperglycemia, suggesting that hepatic IRS1 and IRS2 are the critical mediators of insulin’s regulation of glucose metabolism." (PMID 35074429, 2022). "The results hence demonstrated that oral administration of aqueous extract of Thymus serpyllum can potentially attenuate hyperglycemia in the liver muscle of streptozotocin (STZ)-induced diabetic mice via AMPK and IRS1 upregulation." (PMID 36079819, 2022). "Mice with liver-specific double IRS1 and IRS2 knockout exhibit severe hyperglycemia, suggesting that liver IRS1 and IRS2 are the critical mediators of insulin’s regulation of glucose metabolism." (PMID 33672754, 2021). "CLPr does not show a significant GLUT4 translocation, though it significantly prevented hyperglycaemia estimated by OGTT and IRS-1 phosphorylation in the present study." (PMID 30719284, 2019). "Additionally, insulin receptor substrate 1 (IRS-1) and phosphoinositide-dependent protein kinase 1 (PDK1) are essential for the overall regulation of insulin sensitivity and hyperglycemia management in T2D." (PMID 39857685, 2025). "We identified IRS1 as differentiallyexpressed between patients with or without acute hyperglycemia, but gene expressionwas not influenced by glycemic variability." (PMID 40179269, 2025). "Individuals with hyperglycemia > 200 mg/dL atintensive care unit admission exhibited a downregulation of IRS1 compared tothose without (0.4 [0.1-0.8] versus 1.1 [0.3-2.2], p =0.04)." (PMID 40179269, 2025). "Hepatic IR generates postprandial hyperglycemia in mice lacking insulin receptor substrate 1(Irs1) fed with high-fat diet." (PMID 41473239, 2025). "When IR occurs in the liver, the tyrosine phosphorylation of IRS1 is severely damaged by hyperglycemia, leading to a decrease in the liver’s ability to absorb glucose, affecting proximal defects in the INSR, IRS1, PI3K, and AKT pathways and impairing the insulin transduction pathway." (PMID 39272556, 2024). "Activated JNK (activated, e.g., by hyperglycaemia, free fatty acids, cytokines or ER stress) and ERK1/2 phosphorylate insulin receptor substrate-1 (IRS-1) and thus prevent signal transduction after insulin binding to the insulin receptor, leading to alterations in insulin action." (PMID 37817178, 2023). "ROS which could be augmented by hyperglycemia activate proinflammatory pathways including IKKβ and JNK which subsequently phosphorylate inhibitory sites such as Ser307 of IRS-1." (PMID 33708129, 2021). "In NASH patients, decreased IRS1 expression in the liver could lead to T2DM due to impaired glucose metabolism including fasting hyperinsulinemia and postprandial hyperglycemia." (PMID 29749571, 2018). "This was also consistent with lack of IRS-1 phosphorylation on Ser-24 in hyperglycemia-induced insulin-resistant adipocytes." (PMID 25330241, 2014). "As a consequence, IRS-1 phosphorylation is inhibited leading to lower binding of phosphatidylinositol 3-kinase to IRS-1 and lower translocation of glucose transporter (GLUT-4) to the membrane, stimulated by insulin, with subsequent worsening of hyperglycemia and hyperinsulinemia." (PMID 24084729, 2013).
Hyperglycemia (continued). "Due to skeletal muscle 5′ adenosine monophosphate-activated protein kinase activation, mice lacking IRS1 and IRS2 in cardiac and skeletal muscles did not develop hyperinsulinemia or hyperglycemia." (PMID 40141412, 2025). "A similar result was found in another experiment that involved IRS1 knockout mice lacking hepatic IRS2, it was observed that leptin, IGF1 levels was decreased, glucose tolerance ability was impaired and resulted in hyperglycemia." (PMID 35241081, 2022). "A decrease in hyperglycemia was only observed in taurine-treated mice previously fed a balanced diet, possibly due to taurine reducing the activated form of insulin receptor [phosphorylated IRS-1 (p-IRS-1)] by half, without altering its total protein levels in the murine hypothalamus." (PMID 36699147, 2021).